EDN1 (endothelin 1)
Description:
Endothelins are endothelium-derived vasoconstrictor peptides (By similarity). Probable ligand for G protein-coupled receptors EDNRA and EDNRB which activates PTK2B, BCAR1, BCAR3 and, GTPases RAP1 and RHOA cascade in glomerular mesangial cells. Also binds the DEAR/FBXW7-AS1 receptor. Promotes mesenteric arterial wall remodeling via activation of ROCK signaling and subsequent colocalization of NFATC3 with F-actin filaments (By similarity). NFATC3 then translocates to the nucleus where it subsequently promotes the transcription of the smooth muscle hypertrophy and differentiation marker ACTA2 (By similarity).
Synonyms: PPET1; ET1; ARCND3; HDLCQ7; QME
Tractability: Antibody: its Gene Ontology location is reachable by antibodies, with high confidence; UniProt places it where antibodies can reach, with medium confidence; UniProt predicts a signal peptide or a membrane-spanning region. PROTAC: ubiquitination databases record sites on it.
Safety:
Unwanted effects reported when the protein is acted on. In parentheses: how it was acted on, where the effect was seen, and who reports it.
edema (source: ClinPGx)
Gene: Protein-coding gene on chromosome 6 (12,287,459 to 12,297,194, forward strand). Ensembl gene ENSG00000078401.
Subcellular location: Secreted
Subcellular location (Human Protein Atlas): Golgi apparatus; Predicted to be secreted
Pathways (Reactome):
Signal Transduction: G alpha (q) signalling events; Peptide ligand-binding receptors
Developmental Biology: Transcriptional and post-translational regulation of MITF-M expression and activity
Gene Ontology:
Molecular function: cytokine activity; endothelin A receptor binding; endothelin B receptor binding; hormone activity; protein binding; receptor ligand activity; signaling receptor binding
Biological process: artery smooth muscle contraction; calcium-mediated signaling; cAMP/PKA signal transduction; cell surface receptor signaling pathway; cell-cell signaling; cellular response to hydrogen peroxide; cellular response to toxic substance; endothelin receptor signaling pathway; G protein-coupled receptor signaling pathway; intracellular calcium ion homeostasis; negative regulation of gene expression; negative regulation of phospholipase C/protein kinase C signal transduction; negative regulation of protein metabolic process; negative regulation of transcription by RNA polymerase II; neutrophil chemotaxis; nitric oxide transport; peptide hormone secretion; phosphatidylinositol 3-kinase/protein kinase B signal transduction; positive regulation of calcium-mediated signaling; positive regulation of cardiac muscle hypertrophy; positive regulation of cation channel activity; positive regulation of cell growth involved in cardiac muscle cell development; positive regulation of cell migration; positive regulation of cell population proliferation; positive regulation of cell size; and 92 more
Cellular component: cytoplasm; extracellular region; transport vesicle; basal part of cell; rough endoplasmic reticulum lumen; Weibel-Palade body
Genetic constraint (gnomAD): Loss-of-function variants: 15 observed, 27.49 expected, observed/expected ratio (o/e) 0.55, 90% interval 0.36 to 0.84. The upper end of that interval is the gene's LOEUF score, 0.84, which puts it in group 3 of 6, group 1 being the genes least tolerant of losing a copy. Missense variants: 244 observed, 276.57 expected, observed/expected ratio (o/e) 0.88, 90% interval 0.79 to 0.98. Synonymous variants: 85 observed, 95.66 expected, observed/expected ratio (o/e) 0.89, 90% interval 0.75 to 1.06.
Gene-disease validity (ClinGen):
ClinGen rates the evidence that EDN1 causes each of these diseases.
auriculocondylar syndrome (autosomal recessive): Limited. Auriculo-condylar syndrome (ACS) presents with bilateral external ear malformations ('question mark' ears), mandibular condyle hypoplasia, microstomia, micrognathia, microglossia and facial asymmetry.
Homologues: Orthologues: chimpanzee EDN1 (96% identical), macaque EDN1 (93% identical), dog EDN1 (70% identical), mouse Edn1 (69% identical), pig EDN1 (69% identical), rat Edn1 (68% identical), rabbit EDN1 (67% identical), guinea pig EDN1 (64% identical), tropical clawed frog edn1 (40% identical), zebrafish edn1 (31% identical). Paralogues in human: EDN2 (27% identical), EDN3 (21% identical).
Diseases named in the same sentence as EDN1 in open-access papers:
EDN1 is named in the same sentence as 616 diseases in open-access papers, as found by Europe PMC text mining. Sharing a sentence is not in itself a finding about the gene and the disease. The quoted sentences say what the papers report.
endothelial dysfunction (633 papers, 2007 to 2026). In vascular diseases, endothelial dysfunction is a systemic pathological state of the endothelium (the inner lining of blood vessels) and can be broadly defined as an imbalance between vasodilating and vasoconstricting substances produced by (or acting on) the endothelium. "Glaucoma has been associated with endothelial dysfunction and decreased levels of nitric oxide, endothelin-1 (ET-1), vascular endothelial growth factor (VEGF), and soluble VEGF receptor FLT-1." (PMID 40647700, 2025). "An increased acid load due to low fruit intake increases endothelin-1, which causes endothelial dysfunction and atherosclerosis, and thus, the development of CKD status." (PMID 40362909, 2025). "AP is also associated with endothelial dysfunction (ED), marked by elevated endothelin-1 (ET-1) and intercellular adhesion molecule-1 (ICAM-1), which disrupts vascular integrity and fosters atherogenesis." (PMID 40001895, 2025). "Endothelin-1, also implicated in endothelial dysfunction, was detected in all EC populations (highest in HCAECs) apart from the 3DV hPSC-ECs." (PMID 38775849, 2024). "In endothelial cells, expression of Foxn1 increased in response to endothelin-1, a marker of endothelial dysfunction, and was associated with oxidative stress." (PMID 39061983, 2024). "Endothelin-1 (ET1) is also associated with endothelial dysfunction through its stimulation of nicotinamide adenine dinucleotide phosphate (NADPH) oxidase-derived reactive oxygen species (ROS) production, which inhibits NO-mediated endothelial relaxation." (PMID 38791492, 2024). "IR has been found to be associated with decreased nitric oxide and increased endothelin-1 production, both of which lead to endothelial dysfunction, platelet activation, and thrombosis formation." (PMID 39685728, 2024). "Imbalances between the vasorelaxant nitric oxide and the vasoconstrictor endothelin-1 (ET-1) are a hallmark of endothelial dysfunction and contribute to the progression of vascular diseases." (PMID 38541800, 2024). "IR is associated with decreased nitric oxide and increased endothelin-1 production with resultant endothelial dysfunction." (PMID 39685728, 2024). "TMAO can dysregulate the mechanisms of vasorelaxation by increasing the production of endothelin-1 (ET-1), causing endothelial dysfunction." (PMID 37337893, 2023). "The consequent endothelial dysfunction causes a decrease in nitric oxide (NO), a vasodilator molecule, that generates a relative increase in vasoconstriction factors, mainly endothelin-1 (ET-1)." (PMID 37440588, 2023). "Endothelial dysfunction in glaucoma has been associated with an imbalance between endothelin-1 and NO." (PMID 35745220, 2022). "Endothelial dysfunction is also associated with endothelial expression of many prothrombotic molecules and receptors, including P-selectins, angiopoietin-2, and endothelin-1." (PMID 36034557, 2022). "The ability of these compounds to improve endothelial dysfunction works through enhancing relaxation and suppressing contraction caused by endothelin-1 (ET-1) and increasing NO levels in plasma." (PMID 35408760, 2022). "In particular, TNFα triggers endothelial dysfunction by reducing NO production, which activates the NF-κB pathway, propagates inflammation, increases endothelin-1 (ET-1), and causes vasoconstriction." (PMID 35203265, 2022). "As part of endothelial dysfunction, norepinephrine causes vasoconstriction and function synergistically with endothelin-1 (ET1) as hinted in emotionally triggered cardiac events." (PMID 36420248, 2022). "Endothelin 1 is a well-known potent vasoconstrictor that is highly associated with endothelial dysfunction, and similar results have been previously reported." (PMID 35626723, 2022). "Endothelial dysfunction can be caused by increased blood levels of the vasoconstrictor endothelin-1 (ET-1) with far-reaching consequences." (PMID 36061831, 2022).
endothelial dysfunction (continued). "Endothelin-1 (ET-1), a peptide derived from endothelial cells, has been indicated to be associated with endothelial dysfunction and inflammation." (PMID 35310980, 2022). "The previous study showed that endothelial dysfunction, with increased endothelin-1 (ET-1) synthesis, and sarcopenia, characterized by the loss of muscle mass and strength, are two aging-related conditions." (PMID 35468098, 2022). "Vasoconstrictor molecules are also produced and released by endothelial cells, including Angiotensin II, Prostaglandin, or Endothelin 1, which act as a potent vasoconstrictor and are associated with endothelial dysfunction." (PMID 35626723, 2022). "These factors have been shown to mediate endothelial dysfunction causing the release of endothelin-1 (ET-1) and a decrease of vasodilators, such as nitric oxide, which contributes to the development of hypertension." (PMID 34831040, 2021). "Endothelin-1 (ET-1) is also an endothelial cell-derived factor associated with endothelial dysfunction which has a key role during SLE progression." (PMID 33516274, 2021). "A previous study reports that increased levels of sFlt-1 can induce a PE-like syndrome in rats, linked with increased levels of endothelin 1 and reduced levels of NO, thus resulting in endothelial dysfunction." (PMID 34326776, 2021). "An increase in endothelin-1 and a decrease in NO are representative symptoms of endothelial dysfunction, which are also observed in estrogen-deficient women and ovariectomized animals." (PMID 32595737, 2020). "Plasma von Willebrand factor (vWF; an endothelial activation marker) and endothelin-1 (ET-1; an endogenous vasoconstrictor strongly linked with endothelial dysfunction) were measured." (PMID 33080821, 2020). "Oxidative stress is also associated with endothelial dysfunction and alterations in Endothelin-1 (ET-1) signaling pathways." (PMID 32582590, 2020). "Proinflammatory cytokines from such inflamed fat also stimulates S100A7 and DEfB4A expression and can cause endothelial dysfunction in local blood vessels in part due to inadequate endothelin-1 action." (PMID 32826922, 2020). "Endothelial dysfunction, with increased endothelin-1 (ET-1) synthesis, and sarcopenia, characterized by the loss of muscular mass and strength, are two aging–related conditions." (PMID 32572011, 2020). "In septic patients, endothelial dysfunction measured by plasma endothelin-1 has been shown to be associated with RV dysfunction and E-Selectin with hypotension." (PMID 31247004, 2019). "Endothelial activation was well represented in dSSc samples by the overexpression of gene encoding for endothelin 1 (EDN1) that is associated with diseases characterized by endothelial dysfunction and fibrosis." (PMID 29559981, 2018). "Diminished nitric oxide (NO) production or availability and/or imbalance of relative contribution of endothelium-derived relaxing-contracting factors, like endothelin-1 (ET-1), angiotensin, and oxidants, are associated with endothelial dysfunction." (PMID 28614418, 2017). "On the other hand, lower activation of nitric oxide synthesis and increased synthesis of endothelin-1 cause endothelial dysfunction and proliferation, leading to obliteration of pulmonary vessels." (PMID 27757709, 2017). "Insulin resistance has been proposed as an underlying mechanism that links endothelial dysfunction factors such as endothelial nitric oxide synthase (eNOS) and Endothelin-1 (ET-1)." (PMID 28035952, 2016). "Previous studies have shown that intermittent hypoxia is associated with an elevated plasma endothelin-1 (ET-1) level, endothelial dysfunction and augmented vasoconstriction." (PMID 23555567, 2013). "Insulin resistance has been associated with endothelial dysfunction, and increased secretion of endothelin 1, a potent vasoconstrictor." (PMID 23927768, 2013).
endothelial dysfunction (continued). "The current study shows that pulmonary vasoconstriction is caused by endothelial dysfunction, which is losing the balance between vasodilation (such as nitric oxide and prostacyclin) and vasoconstriction (such as endothelin-1)." (PMID 23554737, 2012). "PTH stimulates vascular smooth muscle cells to produce factors involved in sclerosis, and induces the endothelial expression of factors implicated in endothelial dysfunction, such as endothelin-1 and interleukin-6." (PMID 22937036, 2012). "PHTN pathogenesis involves multifactorial interactions—genetic susceptibility, endothelial dysfunction (reduced nitric oxide bioavailability, elevated endothelin-1), RAAS activation, sympathetic overactivity, sodium retention, and chronic inflammation-driven vascular remodeling." (PMID 40547031, 2025). "Emerging evidence suggests that plaque erosion may be linked to endothelial dysfunction and vasospasm, driven by reduced nitric oxide (NO) bioavailability and elevated endothelin-1 (ET-1) levels." (PMID 41169883, 2025). "An additional factor that could contribute to endothelial dysfunction in middle-aged/older men with low testosterone that is also associated with oxidative stress and inflammation is endothelin-1 (ET-1)." (PMID 39887085, 2025). "Cardiopulmonary bypass (CPB) for corrective surgery may cause endothelial dysfunction, involving endothelin-1 (ET-1), circulating endothelial cells (CECs), and endothelial progenitor cells (EPCs)." (PMID 39201580, 2024). "Among the proposed mechanisms, endothelial dysfunction associated with an increase in endothelin-1 (ET-1) synthesis could promote muscle senescence by altering the proliferative activity of stem cells." (PMID 39335461, 2024). "The endothelin-1 (ET-1) pathway is a key mediator implicated in endothelial dysfunction, however, its regulation in the vasculature of pregnancies complicated by GDM remains unclear." (PMID 37893034, 2023). "Additionally, OW and OB individuals have elevated levels of endothelin-1 (ET-1), a marker of endothelial dysfunction linked to hypertension, chronic kidney disease, and stroke." (PMID 37836527, 2023). "Furthermore, insulin resistance is strongly associated with endothelial dysfunction, marked with an imbalance between nitric oxide (NO) and endothelin-1, two important determinants of arterial stiffness." (PMID 39221025, 2022). "The vasoconstricting peptide endothelin-1 (ET-1) is associated with endothelial dysfunction." (PMID 34600499, 2021). "A recent study revealed that IR could decrease the expression of MicroRNA-21, an important mediator that regulates the secretion of nitric oxide (NO) and endothelin-1, thereby causing endothelial dysfunction." (PMID 34689767, 2021). "In addition, the endothelial dysfunction either associated with hypertension and aging or induced by endothelin-1 (ET-1) can be prevented by pharmacological inhibition of PARP with PJ34." (PMID 32911782, 2020). "Moreover, in a previous study conducted in septic patients, we have shown an association between expressions of ATF6 and ET1 (coding for endothelin-1 which is associated with endothelial dysfunction)." (PMID 33659258, 2020). "Endothelin-1 (ET-1) is associated with endothelial dysfunction and vasoconstriction." (PMID 29743680, 2018). "In addition, high Renalase levels and chronic kidney disease synergistically act to increase endothelin-1 levels, which is associated with endothelial dysfunction and vasoconstriction." (PMID 30181378, 2018). "However, the vascular remodeling (structural changes) in hypertension is also associated with activation of the renin-angiotensin system, endothelin-1, endothelial dysfunction, oxidative stress, and ADMA." (PMID 24795884, 2014).